CD4 (CD4 molecule)
Diseases named in the same sentence as CD4 in open-access papers (continued):
Sharing a sentence is not in itself a finding about the gene and the disease.
tumor (continued). "When examining the role of T-cells in these observations, HDACi was shown to drive trafficking of T-cells to tumours, potentiating the anti-tumour response through CD4+ and CD8+ effector T-cells, whilst decreasing the presence of immunosuppressive immature myeloid cells." (PMID 34439236, 2021). "Tumour-infiltrating CD4+ T cells showed a trending increase in combination-treated mice." (PMID 34784792, 2021). "Furthermore, our research showed that the extent of tumor-infiltrating CD4+ T cells was positively correlated with the expression of TRAF3IP3 (correlation coefficients of 0.55 and 0.54 for the training and validation sets, respectively)." (PMID 34631307, 2021). "Nonetheless, the details of how CD4+ GzmB+ T cells located in the central tumor affects the anti-tumor immunity remains unclear and controversial, especially in pMMR CRC." (PMID 34631551, 2021). "In contrast to other treatment groups, PeptiBAC-Trp2 in combination with anti-PD-1-treated tumors had significantly more tumor-infiltrating CD4+ and CD8+ T cells as well as Trp2-specific CD8+ T cells, indicating an enhanced effect on T cell responses by combining the two treatment modalities." (PMID 34266884, 2021). "Notably, FHPS score was also found to be positively correlated with the CD4+ T cell, which is generally considered as a tumor-toxic T cell." (PMID 34977159, 2021). "However, Tregs, another subset of CD4+ T cells, often inhibit antitumor immune responses and promote tumor growth." (PMID 35111169, 2021). "Since the density of CD4+ GzmB+ T cells may be a promising prediction in pMMR CRC, a verification of the level of CD4+ GzmB+ T cells in the central tumor in an independent data set is needed." (PMID 34631551, 2021). "The scarcity of effector T cells in the tumor is compounded by enrichment of regulatory T cells (Treg), a subpopulation of CD4+ T cells that suppress effector T cells through cytotoxic T lymphocyte–associated protein 4 (CTLA-4) signaling and secretion of cytokines TGF-β and interleukin-10." (PMID 33496872, 2021). "Sarcomatoid tumors show fewer CD4+ and CD8+ T cells in the tumor and are characterized by a loss of Th1 features such as T-bet (marker for Th1 polarization) and granzyme B expression, which are required for an efficacious anti-tumor immune response." (PMID 34249695, 2021). "Moreover, the blockage of TGF-β signaling in CD4+ T cells of mice promoted a Th2 cell-differentiation program and reduced tumor growth." (PMID 34262562, 2021). "In summary, tumor grading is correlated with CD4+ T-cell infiltration and CIITA expression." (PMID 34359808, 2021). "According to our results, LINC00987 and A2M might inhibit tumor growth by suppressing mast cells and memory CD4 T-cells and promoting the conversion of M0 macrophages to M1 and M2." (PMID 33987201, 2021). "In addition, the EZH2 and H3K27me3 levels are increased only in Treg cells when compared to CD4+Foxp3- T cells in tumor tissues." (PMID 33868269, 2021). "The tumor cell fragments formed after apoptosis are absorbed by local dendritic cells and migrated to the draining lymph nodes, thus inducing tumor-specific CD4+ and CD8+T cells to migrate to the tumor site, producing the acquired immunity and stimulating the anti-tumor activity." (PMID 33935714, 2021). "Moreover, within the tumor region, they had a lower density of total CD4+ cells and a lower CD4 + FoxP3+/CD8 + Granzyme B+ cell ratio." (PMID 33947438, 2021). "MDSCs are a heterogeneous population of immature myeloid cells that are recruited to the primary tumor as well as metastatic sites and play a crucial role in inhibiting innate and adaptive immune responses by suppressing CD4+ T cells, CD8+ T cells, and natural killer (NK) cells." (PMID 34541363, 2021). "Besides, the efficacy of tumor immune surveillance and deregulation of tumor growth depends on the presence of suppressor and regulatory CD4+ T cells in tumor tissue, para-tumor tissue or peripheral blood." (PMID 33996273, 2021).
tumor (continued). "Furthermore, as the significant correlation in tumor infiltrating cell except CD4 + cell, correlation of B cell, T cell CD8+, M1 and M2 macrophages, neutrophil cells, and dendritic cells markers with NPC2 expression were analyzed." (PMID 33777094, 2021). "Under anti–PD-1/PD-L1, CD8 proliferation could be enhanced through direct blockade of PD-1 on CD8 T cells and through reinvigoration of the helper activity of tumor Ag–specific CD4 T cells." (PMID 33332284, 2021). "Importantly, tumour cells isolated from the CD4-NPM-ALK transgenic mice exhibited reduced proliferation when treated with Imatinib, a tyrosine kinase inhibitor which targets PDGFRβ." (PMID 33413671, 2021). "Indeed, visualising these cell types showed that Type 1 macrophages are found often in close proximity to CD4+ T cells and DCs, particularly at the edge of the tumour." (PMID 34625563, 2021). "Notably, analyses of tumor-infiltrating lymphocytes indicated that treatment with melatonin significantly increased the number of CD3 + CD4+ and CD3 + CD8+ T cells, but reduced infiltration of Ly6G + F4/80- myeloid-derived suppressor cells (MDSC)." (PMID 34073318, 2021). "Still, treatment of single patients with clonal or bulk TIL-derived CD4+ T cells already suggests that infusion of large numbers of CD4+ T cells, might, at least in certain cases, suffice for controlling tumor growth." (PMID 33546283, 2021). "Taken together, these results demonstrate that TLS-B cell density correlates with a specific transcriptional gene signature associated with Th1/memory response and GC formation, as well as with decreased proliferative capacities, chemotaxis, and Treg functions in tumor-infiltrating CD4+ T cells." (PMID 33763071, 2021). "Therefore, we isolated exosomes from 4T1 tumor-bearing splenic cells, tumor-associated cells, tumor-infiltrating CD8+ T cells and CD4+ T cells." (PMID 34172932, 2021). "We also found that the PBK level was significantly correlated with the degree of infiltration of M0 and M1 macrophages, T cells CD4 memory activated, and T cells follicular helper, consistent with the tumor microenvironment analysis that PBK is negatively related to immune infiltration." (PMID 34859049, 2021). "The analysis of CD4 + T cell subsets reveals for the mrHCC2 subgroup a minimal immune suppressive Treg cell profile, with a maximal naïve, memory resting and follicular helper cells signature, suggesting a robust control of anti-tumor immune responses." (PMID 34234215, 2021). "Furthermore, a subset of genes expressed by CAFs was found to increase the proportion of CD4+FOXP3+ regulatory T cells (Tregs) creating an immunosuppressive tumour microenvironment that prevent the tumour-reactive immune responses." (PMID 34681023, 2021). "Similar to the conventional APC, B cells express MHC class II molecules on their surface and are, hence, capable of antigen presentation to CD4+ T cells for activation, and cognate interaction between T and B cells induce differentiation of anti-tumor Tfh cells." (PMID 34012451, 2021). "Then the pulsed dendritic cells could induce T cells’ dependent anti-tumor response, including CD4+ and CD8+ T cells." (PMID 33922480, 2021). "Using a 56-marker CODEX panel, unsupervised machine learning, and manual curation based on marker expression, tissue localization, and morphology, 21 unique cell types were identified and validated, including reactive CD4+ T cells and malignant CD4+ T cells (i.e., tumor cells)." (PMID 34795254, 2021). "However, the interplay between polyfunctional CD4+ T cells and other immune cell lineages within the context of tumor immunity is not well understood." (PMID 34298668, 2021). "The killing effect of CD4+ T cells on tumor is mainly mediated by IFN-g-dependent mechanism." (PMID 33585490, 2021). "Importantly, CD4+ T cells are responsible for priming and expanding tumor-specific CD8+ T cells through the delivery of survival signals and maintaining long-term CD8+ T cell memory responses." (PMID 34548096, 2021).
tumor (continued). "The correlation between gut diversity and increased tumor infiltration of CD4+ lymphocytes suggest that patients harboring a more diverse gut microbiota at baseline may benefit from CRT to a greater extent." (PMID 33619320, 2021). "Thus, we propose that serum CD4 can be used to evaluate immune status in the tumor microenvironment." (PMID 34258299, 2021). "CD4+ TNFR2+ lymphocytes were reported as Tregs that contribute to tumor progression." (PMID 34201054, 2021). "Similarly, YYWY exerted the anti-tumor effect by inducing DCs mature, which subsequently activated CD4+ T lymphocytes and enhanced Th1 function." (PMID 34722304, 2021). "In support, previous studies have shown that MTR chemotherapy induces immunogenic cancer cell death, which releases danger signals that promote DC maturation and presentation of tumor antigens to CD4+ T cells, polarizing them towards antitumor IFN-γ-producing T helper 1 (Th1) responses." (PMID 33920884, 2021). "Taken together, these data raise the possibility that the immune milieu of involution group tumors is characterized by low CD4 and high myeloid populations, which could result in impaired anti-tumor cytotoxic immunity." (PMID 33916683, 2021). "On the other hand, however, functional specialization of CD4 T cells towards other polarities may have the opposite effect and promote tumor growth and dissemination." (PMID 34064410, 2021). "In addition, we found that most of the tumor cells were quiescent in recurrence-free patients, and that there was a significant infiltration of CD4+ T cells around the lesions of the pancreatic duct (follow-up time (FT) >3 years)." (PMID 34485300, 2021). "Moreover, the use of a LP also allows presentation via MHC II of antigen-presenting cells, and thus the stimulation of CD4+ lymphocytes, allowing a more effective immune response against tumor cells." (PMID 34885150, 2021). "Indeed, distinct immune microenvironments coexist within the same tumor and higher variability of T-cell infiltration and type (CD8+, CD4+ and Treg cells) exists within a tumor than across tumor sites and patients." (PMID 34140011, 2021). "And the GMPS expression was related to tumor purity, CD4+ T cells and neutrophils." (PMID 34520390, 2021). "CD4+ T cells detected by FC were also similarly abundant in the tumor and the CSF." (PMID 33686071, 2021). "An earlier study has shown convincingly, using flow cytometry and fluorescent markers, that tumor cells and CD4 + T cells could exchange their own cytosol content, which may result in remarkable functional consequences." (PMID 34554502, 2021). "Notably, those patients delivering TR TILs presented a significantly higher frequency of CD8+ and CD4+ lymphocytes in the fresh tumour." (PMID 33402737, 2021). "However, no clinical trials have assessed the effectiveness of fingolimod in cancer, potentially due to the impairment of cytotoxic CD8+ T and CD4+ T cell trafficking and activation, which precludes tumor infiltration to kill cancer cells." (PMID 34737957, 2021). "Even though positively correlated with elevated AFP and poor tumor differentiation, CD4+ TILs were discovered to be associated with neither overall survival nor disease-free survival." (PMID 34566989, 2021). "Once presented on the cell surface, they are referred to as neoantigens and could act as targets for tumour-infiltrating CD4+ helper T lymphocytes and CD8+ cytotoxic T lymphocytes (CTLs)." (PMID 34067951, 2021). "In addition, these specific genera were associated with increased intratumoral immune infiltrates mediated by the recruitment of CD4+T cells into the tumor bed and increased ratio of CD4+T cells to Tregs in response to PD-1 blockade." (PMID 35003090, 2021). "Flagellin could also significantly suppress tumor cell proliferation and decrease the frequency of CD4+, CD25+ regulatory T cells." (PMID 34138211, 2021). "It produces tumor-reactive antibodies and primes CD4+ and CD8+ T cells." (PMID 34804955, 2021).
tumor (continued). "Importantly, TNF-α and IFN-γ synergistically induced signaling in CD4+ T cells that prevents immune evasion, tumor cell proliferation, and multistage carcinogenesis." (PMID 33957948, 2021). "Similarly, LSM3 expression was correlated with tumor purity (r = 0.191, p = 1.29 × 10−9) and CD4+ T-cell markers (r = −0.143, p = 8.24 × 10−6)." (PMID 34638387, 2021). "Also, lower CD4+/CD8+ T-cell ratios were found in the tumor samples with high network GSVA scores than in the tumor samples with low scores." (PMID 34630508, 2021). "Moreover, coexpression of Cxcl1 and Ccl2 efficiently attenuated activation of CD8+ and CD4+ T cells in tumour cells ectopically expressing USP12, as evidenced by the changes in the frequencies of TNF-α+IFN-γ+ cells in the populations." (PMID 34381028, 2021). "While the effect of T-cells on disease outcome has been well defined, with cytotoxic CD8+ T cell infiltration correlating with favorable outcomes in multiple studies and CD4+ subsets sustaining effective anti-tumor immunity, the role of B-cells is yet to be fully understood." (PMID 34771546, 2021). "Hence, a new role was suggested for tumor-infiltrating B cells in their interplay with CD4+ TIL in the TME." (PMID 34641822, 2021). "CTLA-4 is crucial at the priming stage of naïve anti-tumor T cell responses by professional antigen presenting cells (APC), and therefore its blockade has the potential to generate de novo powerful CD8+ cytotoxic and CD4+ helper T cell anti-tumor effector responses." (PMID 35069536, 2021). "However, CD8+ and CD4 + T cells get a lower frequency in the tumor microenvironment, and their phenotype is related to immune failure." (PMID 34845974, 2021). "Traditionally, effective adaptive immune response against cancer requires the rendezvous between the tumor antigen/major histocompatibility complex expressed on mature dendritic cells (DC) traveling from the primary tumor site and the resident CD4+ and CD8+ T cells in the secondary lymphoid organs." (PMID 34267760, 2021). "Importantly, CD8+ iTregs conditionally suppress allogeneic reactions without impairing general immunity against pathogen infection and residual tumor recurrence, in contrast to unselective CD4+ Tregs." (PMID 34899714, 2021). "CD4+ T lymphocytes can both inhibit tumor growth and promote tumor growth." (PMID 33816234, 2021). "However, they were found to have in common the secretion of IL-10 and TGF-β, which renders them able to convert conventional CD4+ T cells into Tregs, and thus subvert several immune effectors at the tumor site." (PMID 33804027, 2021). "For example, in human BC xenografts in humanized mice, blocking the recruitment of naive CD4+ T cells in the tumor by knocking down the expression of PITPNM3, a CCL18 receptor, significantly reduced intragranular regulatory T cells and inhibited tumor progression." (PMID 34257557, 2021). "This has direct effects on anti-tumour immunity, where coincident activation of CD4 and CD8 T cell responses leads to higher magnitude CD8 T cell responses and better clinical outcomes as compared to activating CD8 T cells alone; augmenting costimulation appears to be critical for this." (PMID 34899742, 2021). "To test this hypothesis, we examined MB49 tumor growth in athymic nude C57BL/6 mice as they lack CD4 and CD8 T-cells." (PMID 33986291, 2021). "Transfer of CD8αβ in combination with intermediate affinity tumor reactive αβTCR has been reported to support tumor control in vitro and in vivo, and for high affinity αβTCR with artificial signaling domains adding CD8α alone has been shown to reprogram CD4+ T cells." (PMID 34759930, 2021). "CD8+ and CD4+ T cells infiltrations in tumor sites were also confirmed by IHC." (PMID 34794428, 2021). "This was also seen for total CD4+ T cells per mg of tumor, which increased to a ratio of 13:1." (PMID 33651712, 2021). "However, the patients with more CD4+ T th2 infiltration in the tumor tends to have worse prognosis (Log-rank test, P=0.016)." (PMID 33910272, 2021).
tumor (continued). "Indeed, overall we found a significant correlation between a reduction in CD3 + and CD4 + T-cell numbers and a reduction in tumour cell content in tumour biopsies after 1 cycle of treatment." (PMID 33983492, 2021). "In young mice, stress reduced tumor CD4+FoxP3+ cell infiltration (p<0.03)." (PMID 34604038, 2021). "Our results indicated that low-dose dexamethasone may also enhance anti-tumor immunity by decreasing PD-L1 on surface of CD4+ lymphocytes." (PMID 34175886, 2021). "Similarly, a recent study in orthotopic KPC tumours showed that the expression of PD-L1 (B7-H1) was expressed in approximately 40% and 60% of CD4+ and CD8+ T cells respectively." (PMID 34140952, 2021). "We showed here that combination of KISIMA vaccination therapeutic protein vaccine with subcutaneous STINGa treatment profoundly impacts both quantity and quality of CD8 and CD4 T cells, which resulted in a prolonged control of tumor growth in both B16-OVA and TC-1 tumor models." (PMID 34276686, 2021). "We can hypothesize that TLS-B cells positively modulate anti-tumor T cell immunity by limiting CD4+ Treg generation, while favoring CD4+ T cell activation and restraining CD4+ T cell exhaustion." (PMID 33763071, 2021). "Data presented here show that PD-1 blockade could in addition indirectly contribute to tumor-specific CD8 T cell proliferation through in situ reactivation of tumor Ag–specific PD-1hiCD39+ CD4 Tconv TILs and DC maturation." (PMID 33332284, 2021). "Similarly, cleaved caspase 3 levels were unchanged in CD4-NA mouse tumour cell lines treated with siRNA-targeting BRG1." (PMID 35008316, 2021). "In addition, the absolute number of CD8+ and CD4+ tumor-infiltrating lymphocytes was significantly higher in the neoadjuvant treated patients than in the treatment-naïve group." (PMID 33920544, 2021). "These gene expression changes in tumor infiltrating CD4+ T-cells may be mediated by epigenetic events such as DNA methylation." (PMID 34012510, 2021). "Indeed, we recently identified CD4 T cells with cytotoxic phenotypes involved in the direct elimination of tumor cells in different human cancer types." (PMID 34064410, 2021). "While the anti-tumor activity of CD8+ T cells is well documented, emerging literature details essential anti-tumor activities of CD4+ T cells, including their ability to generate tumor-specific cytolytic responses and mediate the anti-tumor response through the production of cytokines." (PMID 34064933, 2021). "The possible role of the activation of the AICD pathway by IFN-γ in HPD is supported by a study in which two hyperprogressive patients displayed depletion of the immune-cell populations involved in tumor clearance, including monocytes, central memory CD4+ T cells, NK cells and activated DCs." (PMID 33467713, 2021). "Having found that the protein α1PI promotes migration of immature DPs and mature CD4+ T cells through tissue in humans, we sought to develop an orally available small molecule, Alphataxin, to act as a surrogate for α1PI in addressing the effects of CD4+ T cells on tumor killing function." (PMID 34900690, 2021). "Since CD4+ T cells polarization is epigenetically regulated, characterization of immune cells infiltration at tumor site may be assessed by epigenetic analysis." (PMID 34262562, 2021). "In addition to CTLs, CD4+ helper T cells present in the TME are involved in activating CTLs against tumor cells." (PMID 34572263, 2021). "CD4+ T lymphocytes elicit a vigorous anti-tumor immune response." (PMID 34790044, 2021). "In addition, Th17 cells and Tregs, which are subsets of CD4+ cells, maintain immunological self-tolerance and dampen anti-tumor activity in the TME, which is pro-tumorigenic in OvCa." (PMID 34248988, 2021). "CD8+ T cells and CD4+ T cells were crucial for tumor progression." (PMID 34367282, 2021).